CD4 (CD4 molecule)
Diseases named in the same sentence as CD4 in open-access papers (continued):
Sharing a sentence is not in itself a finding about the gene and the disease.
tuberculosis (continued). "In spite of the fact that, several studies have been done on assessment and examined general tuberculosis and HIV co-infection, they didn't deal with the joint determinants of tuberculosis status and CD4 cell count using joint modeling." (PMID 38974259, 2023). "In summary, Th1 CD4+ and CD8+T cell activation in tuberculosis amplify macrophage activation and necrosis, while Th17 promotes neutrophil-mediated tissue necrosis, which drives lung inflammation, tissue damage, and remodeling." (PMID 37415827, 2023). "Impaired CD4- and IgG-specific responses to SARS-CoV-2 antigens have also been observed in PWH with active tuberculosis." (PMID 35975942, 2023). "In 2010, pregnant women and patients co-infected with tuberculosis (TB) presenting with CD4 ≤ 350 cells/μL were eligible to initiate ARV, while the CD4 ≤ 200 μL remained in place for others and the diagnosis of VL failure now required two consecutive VLs of ≥1000 copies/mL three months apart." (PMID 37685268, 2023). "CD4+ T cell plays an important role both in the pathogenesis of HIV and the defense of tuberculosis." (PMID 36901567, 2023). "This approach has proven successful at getting CD4 and CD8 T cells into the vagina and the lungs and provides protection against HSV-2 and tuberculosis, respectively." (PMID 37258506, 2023). "To obtain a panoramic transcriptional profile of T cells, we performed single-cell RNA-sequencing analysis of CD4+ T and CD8+ T cells isolated from peripheral blood mononuclear cells of healthy individuals and patients with tuberculosis." (PMID 36916943, 2023). "In the murine tuberculosis model, such LVs induced efficient MHC-II antigenic presentation and triggered both CD8+ and CD4+ T cells at the systemic and mucosal levels." (PMID 36104497, 2022). "Recombinant BCG was found to induce robust MHC class II-dependent antigen presentation on CD4 T cells in vitro, activating TLR2 and thus leading to a better protection against tuberculosis in mice." (PMID 36295826, 2022). "HIV-related mortality was most predominant in patients with hospitalisation, low CD4 count, advanced WHO stage and tuberculosis co-infection at enrolment." (PMID 34991496, 2022). "Our results were similar to those of a South Korean study conducted in patients with CD4+ T-cell count < 200 cells/μL, which also had IRIS mostly related to tuberculosis." (PMID 36700216, 2022). "CD4 count was < 100 cells/mm3 in 1576 (26%) participants, 3715 (40%) participants were WHO stage III/IV, 539 (6%) had tuberculosis co-infection, and 631 (6%) had arterial hypertension." (PMID 34991496, 2022). "More importantly, it was clearly showed that increased of CD4+ and CD8+ T cells in the lung of rBCG-DisA immunized mice after M. tuberculosis i.n infection implying significant T cell infiltration against infection." (PMID 36081510, 2022). "In humans, airway challenge with the purified protein derivative (PPD) induces CD4+ Trm cells in BALF, highlighting the potential of Trm targeting in vaccines for tuberculosis." (PMID 36009042, 2022). "The risks of tuberculosis and talaromycosis in FUO-HIV patients were high when their CD4 counts were below 50 cells/mm3." (PMID 35042469, 2022). "MDSC counts correlated positively with HIV viral load in plasma as well as M. tuberculosis antigen load in tissue but were inversely correlated with peripheral CD4 T-cell counts, which may indicate a role for MDSCs in TB/HIV disease progression." (PMID 35092727, 2022). "Meanwhile, T cells divide into CD4+ T cells and CD8+ T cells after the stimulation of tuberculosis antigen." (PMID 36504851, 2022). "Mice immunized by subcutaneous injection of tuberculosis subunit vaccine (CAF01 + H56) in the presence of RA showed intensive mucosal H56 specific IgA response and ameliorative Ag-specific CD4+ T lymphocyte homing to lung." (PMID 36504851, 2022).
tuberculosis (continued). "In the context of tuberculosis field, BCG has been demonstrated to be able to induce antigen-specific Th1-type CD4+ T cells with production of IFN-γ, IL-2 and TNF-α, which is considered to exert the protection against M.tb infection." (PMID 36387134, 2022). "This study aimed to investigate the expression and clinical significance of negative costimulatory molecules programmed death-1 (PD-1) and programmed death ligand 1 (PD-L1) on CD4+CD25+CD127low regulatory T cells (Tregs) in peripheral blood of patients with active pulmonary tuberculosis (TB)." (PMID 36035072, 2022). "Eight (44%) had tuberculosis, 7 (39%) malignant lymphoma, 2 (11%) hepatitis B and 1 (6%) hepatitis C. Median CD4 count at diagnosis was 97 cells/mm3 (IQR = 50–130); 94% had CD4 <350 cells/mm3." (PMID 35916394, 2022). "A further limitation was the relatively poor quality and completeness of data on CD4 levels and ART during previous tuberculosis treatment." (PMID 34766068, 2021). "The median CD4 count at HIV diagnosis was 237 cells/μL (IQR: 100 to 430), and 6.6% reported ever having tuberculosis." (PMID 33605061, 2021). "From the background above, the purpose of this study was to see the relationship between the role of adaptive immunity, namely expression mRNA gene Treg, Treg protein levels, CD4 +, and CD8 + to the Tuberculin Skin Test (TST) in tuberculosis children." (PMID 33384873, 2021). "TB-IRIS is characterized by a paradoxical deterioration of tuberculosis manifestations or even the development of new tuberculosis symptoms in HIV-infected patients after the start of ART, despite the increase in CD4+ cells and decrease in viral load." (PMID 34835417, 2021). "Low CD4 cell counts, ART initiation as an inpatient, WHO clinical stage III, and anti-tuberculosis treatment within 90 days of ART initiation were strongly associated with attrition." (PMID 34504234, 2021). "Numerous studies revealed that mycobacterial Ags Rv2628, Rv1737, Rv2029c, and Rv2004 elicit CD4+ and CD8+ T-cells and hence IFN-γ in LTBI individuals compared to those with active tuberculosis." (PMID 34637683, 2021). "While novel concepts for TB vaccination are emerging, these data suggest that the rational design of novel TB vaccines relying on cytokine-producing CD4+ T cells requires a better understanding of the crucial components of an effective CD4+ T cell response against M. tuberculosis infection." (PMID 34554927, 2021). "From these, male sex, advanced age, Tuberculosis (TB) co-infection, low baseline CD4 count, low body mass index, pre-ART viral load, advanced disease stage, bedridden or ambulatory functional status, and low baseline hemoglobin level were stated as independent predictors of mortality." (PMID 33989330, 2021). "Case numbers were too low to study the effect of ART, isoniazid preventive therapy, CD4 cell count, HIV plasma viral load, IFN-γ release assay status, tuberculosis symptoms, and other clinical variables on RISK11 performance." (PMID 33862012, 2021). "Lung resident CD4 TRM, cells induced by various tuberculosis (TB) vaccines mediate protection against M. tuberculosis challenge in animal models." (PMID 33096737, 2020). "CD4+ T cells have long been known to play an important role in immune containment of mycobacterial infection such as M. tuberculosis, proven by increased susceptibility to TB in mice lacking CD4+ T cells." (PMID 32375214, 2020). "Three of the cases diagnosed with tuberculosis granulomas were HIV-positive; all had CD4 counts less than 200 cells/μL." (PMID 32158640, 2020). "The HIV-mediated depletion of CD4 T cells that typically confers a protective immune response to M. tuberculosis infection is likely a main driver of the increased prevalence of active TB in countries with a high HIV burden (5, –, 7)." (PMID 32098821, 2020). "Children who had a baseline CD4 count below threshold had a more advanced HIV clinical stage (p=0.03), and they were more likely to have Tuberculosis (p<0.01)." (PMID 33911825, 2020).
tuberculosis (continued). "In analyses adjusted by STAMP trial arm only, age, sex, time on ART, advanced HIV, BMI, Karnofsky score, CD4 count, haemoglobin, WHO danger signs, tuberculosis treatment, and virological failure were all strongly associated with increased mortality." (PMID 32890497, 2020). "Human immunodeficiency virus infection is the most common risk factor for severe forms of tuberculosis (TB), regardless of CD4 T cell count." (PMID 32730321, 2020). "Baseline CD4 count (AHR = 0.99, 95% CI [0.98–0.99]), Severe acute malnutrition (AHR = 15.92, 95% CI [5.34–47.50]), and exposure to tuberculosis treatment (AHR = 2.93, 95% CI [1.39–6.17]) were the independent predictors for the development of OIs." (PMID 32126978, 2020). "Men or women in need of treatment either had a CD4 count <350/<500 or WHO disease stage 3 or 4, or had tuberculosis." (PMID 31730168, 2020). "Yet, TB progression in HIV-infected individuals occurs at a higher rate even among those with healthy CD4+ T cell counts (11, –, 13), suggesting that other immune factors may contribute to the loss of M. tuberculosis control." (PMID 32434838, 2020). "On the other hand, in a similar tuberculosis model using a different antigen, immunisation with a recombinant adenovirus vector induced mostly CD8+ T-cell responses and only weak CD4+ T-cell responses." (PMID 32775465, 2020). "IFN-γ+IL-21+ CD4 T cells also occur in chronic lymphocytic choriomeningitis virus (LCMV), tuberculosis, and Listeria infections." (PMID 32634740, 2020). "She had been on effective ART for 4 years (CD4+ 200 cells/mm3; VL-LDL) and had been treated for tuberculosis twice, at least 2 years prior to the diagnosis of HIV and the onset of MG symptoms." (PMID 32973647, 2020). "Concerning tuberculosis (TB) starting early could be relevant for mortality only in presence of a CD4+ cell count <50 cells/uL, while in TB meningitis starting earlier led to a greater incidence of side effect without no survival benefit." (PMID 31560700, 2019). "In the comparison of HEC ratio, tuberculosis patients’ tissue group showed higher ratio than CD8 or CD4 groups, and that of CD8 group was higher than in CD4 group." (PMID 31173489, 2019). "In the present study, we studied the immune repertoire of CD4+, CD8+ T cells of patients and healthy controls and tissue sample of patients to elucidate the effect of tuberculosis on patients’ immune system." (PMID 31173489, 2019). "In tuberculosis patients, the HEC number was higher in the tissue group than that in the CD8 group or the CD4 group, while the comparison between the CD4 and CD8 groups showed no statistical difference." (PMID 31173489, 2019). "In the tuberculosis patient group, there were also six TRBV/TRBJ combinations which were used more than 0.5% in CD4 group, and 21 high expression TRBV/TRBJ in CD8 group, and 32 high expression TRBV/TRBJ in tissue group." (PMID 31173489, 2019). "We report the case of a 41-year-old man with HIV (CD4 of 144 cells/dL) and HCV with hematochezia due to tuberculosis in the ileocecal valve and descending colon and CMV tissue invasive disease in the esophagus and descending colon." (PMID 29991949, 2018). "The logistic regression models controlled for sex, age, severe poverty (living on <$1 USD per day), Port-au-Prince residence and baseline clinical characteristics of weight, CD4, WHO stage and tuberculosis diagnosis." (PMID 30453995, 2018). "However, detailed information of different specimens such as for viral load, Tuberculosis (TB) genexpert, EID and CD4 tests linked through specimen referral network is limited." (PMID 30382888, 2018). "Accordingly, subjects with latent M. tuberculosis infection had a lower proportion of responding CD4+ TCNP cells in the peripheral blood, than tuberculosis patients." (PMID 30559746, 2018).
tuberculosis (continued). "Animal models of tuberculosis (TB) and human studies show that CD4 T cells, and especially those that have differentiated into antigen-specific Th1 cells, are necessary for immunological control of the intracellular bacterium, Mycobacterium tuberculosis (M. tb) [reviewed in Ref." (PMID 29545791, 2018). "On the other hand, it was reported that CD4+ Treg cells and CD8+ Treg cells were increased in tuberculosis patients and after BCG vaccination." (PMID 30261082, 2018). "Our findings suggest that CD4+Foxp3+ cells play a time-dependent role in tuberculosis and highlight that CCR4 plays a critical role in the balance of IFN-γ-mediated inflammation by regulating the influx and function of CD4+Foxp3+ cells." (PMID 30584243, 2018). "Each possible pair of capture and detection antibodies (100 pairs in total) was assessed for its ability to detect purified LAM from cultured M. tuberculosis and urinary LAM in urine sample from two TB-positive HIV-positive human subjects with low CD4 blood counts." (PMID 30257899, 2018). "The following routinely collected data were used as predictors in two logistic regression models (one to predict death and another to predict LTF): age, gender, weight, CD4 count, WHO Stage, and diagnosis of tuberculosis (TB)." (PMID 30157197, 2018). "In human trials, CD4+ T-cell polyfunctionality correlated with protection induced by many vaccines, including human immunodeficiency virus (HIV), tuberculosis (BCG vaccine), malaria, and melanoma [31–33, S1]." (PMID 29529222, 2018). "Finally, adaptive immunity such as Th1/Th17 responses mediated by M. tuberculosis-specific CD4+ T cells become involved, which plays a pivotal role in the control of TB progression." (PMID 29868514, 2018). "For example, POC CD4 testing for HIV reduced time to antiretroviral therapy (ART) initiation in Mozambique, and GeneXpert® POC tuberculosis (TB) testing reduced time to multi-drug resistant TB diagnosis in South Africa." (PMID 29751798, 2018). "This confirmed initial results and led us to the conclusion that impaired mIL-7R expression of T cells resulted in increased proportions of mIL-7Rlow CD4+ and CD8+ T cells in tuberculosis patients." (PMID 28582466, 2017). "Development of an ideal vaccine against pulmonary tuberculosis (TB) may require immunization strategies that generate a high frequency of antigen-specific CD4 and CD8 T cell response in the periphery and in the lung." (PMID 29085809, 2017). "Although many experimental vaccines generate memory CD4+ T cells and can control the growth of Mycobacterium tuberculosis (Mtb) early during infection, none reliably provide protection from pulmonary tuberculosis (TB) that is durable." (PMID 29176787, 2017). "Routinely collected data on current and previous ART regimens, CD4 count, WHO clinical stage, anthropometric measurements and history of tuberculosis were extracted from the electronic database." (PMID 29155891, 2017). "CD4+ cells play a pivotal role in both HIV and Mycobacterium tuberculosis (M.tb) infection, and the peripheral blood CD4+ lymphocyte count (CD4 cell count) played an important role historically in ART initiation guidelines and has been shown to be a strong predictor of TB risk." (PMID 29259846, 2017). "Fortunately, many HIV programs routinely collect common patient variables such as age, sex, marital status, pregnancy status, weight, CD4+ count, WHO disease stage, history, and current tuberculosis (TB) status among other parameters." (PMID 28419097, 2017). "To investigate whether ROP could be recognized by CD8+ T cells, we tested PBMCs from human immunodeficiency virus (HIV) and tuberculosis (TB) co-infected patients who had a depleted CD4+ T cell population but a normal CD8+ T cell population." (PMID 29100330, 2017). "Analysis of mIL-7R on T-cell subpopulations revealed increased proportions of mIL-7Rlow CD4+ (p = 0.006) and CD8+ T cells (p = 0.02) from tuberculosis patients as compared to healthy contacts." (PMID 28582466, 2017).
tuberculosis (continued). "This study was also the first to show that BCG elicits polyfunctional CD4+ T cells in both the murine TB model, in which BCG mediates a degree of control of bacterial replication after Mycobacterium tuberculosis (Mtb) challenge, and in humans, as discussed further below." (PMID 29051764, 2017). "In South Africa, for example, treatment is available only for those with low CD4 cell counts (CD4≤500 cells/μL), and is prioritised for those with even lower CD4 counts (CD4≤350 cells/μL), severe disease and HIV/tuberculosis co-infection." (PMID 27391129, 2016). "tuberculosis challenge, the vaccine stimulated the highest proportion IFN-γ+IL-2+TNF+ and CD4+IL-2+TNF+ CD4+ T cell compared with adjuvant-treated or BCG-treated mice as well as the highest proportion of vaccine-specific CD4+ T cells producing IL-17." (PMID 29263854, 2016). "Immunological disruptions within this delicate balance, such as CD4+ T-cell and tumor necrosis factor (TNF) neutralization, can lead to increased tuberculosis pathology." (PMID 27462092, 2016). "Of the 6 etiologic groups with different infections, CMV-infected patients had the lowest median CD4 cell count 22.50 (IQR, 7.50–82.00) while the patients with tuberculosis (TB) infection had the highest CD4 cell count 61.00 (IQR, 27.00–176.00)." (PMID 27227959, 2016). "Central memory T cell (Tcm) and polyfunctional CD4 T cell responses contribute to vaccine-elicited protection with both human and bovine tuberculosis (TB); however, their combined role in protective immunity to TB is unclear." (PMID 27799930, 2016). "The median CD4 cell count was 32 (IQR; 16–101)/mm3; 10 (76.9 %) were taking ART and only one patient was previously treated for tuberculosis." (PMID 27495002, 2016). "In several case series, the main predictor for survival was the prompt initiation of effective anti-tuberculosis treatment, ART, CD4 count, site of the disease, and other previous or concurrent opportunistic infections caused by immunosuppression." (PMID 27561794, 2016). "Triaging HIV treatment is becoming increasingly complex, with different considerations by CD4+ cell count, HIV disease stage, pregnancy status, coinfections with tuberculosis or hepatitis, and the HIV status of a cohabiting sexual partner." (PMID 27367487, 2016). "CD8+ T cells are important for enforcing latency of tuberculosis, and for Mtb control in patients with HIV and low CD4 counts." (PMID 26745507, 2016). "It was also reported that CD4-positive cells that express both IFN-γ and IL-17 were observed in the peripheral blood and pleural fluid from patients with tuberculosis." (PMID 26784959, 2016). "Standardized questionnaire, spirometry, incremental shuttle walk testing, CD4+ cell count, HIV viral load and sputum culture for tuberculosis were performed." (PMID 27662546, 2016). "We analyzed the parameters: age, gender, comorbidities, lipid profile, CD4 cell number; also the number of concomitant HIV drugs, tuberculosis (TB) drugs and drugs for other comorbidities, patients in lipid-lowering treatment." (PMID 27356504, 2016). "In tuberculosis co-infected patients with CD4 cell counts ≤50 cells/mm3 or with CD4 cell counts >50 cells/mm3 who have severe clinical disease, ART should be initiated within 2 weeks of starting tuberculosis treatment." (PMID 25908935, 2015). "HIV infection decreases the number of CD4+ lymphocytes, so it is quite probable that an HIV+ patient can acquire or reactivate tuberculosis disease." (PMID 25983849, 2015). "Although the role of CD8+ T cells in TB is less understood than that of CD4+ T cells, CD8+ T cells were recently hypothesized to markedly contribute to optimal immunity and protection against M. tuberculosis." (PMID 26398213, 2015). "We enrolled 33 subjects with active tuberculosis of which 16 were HIV positive and all were ART naïve with a mean CD4 count of 310 ± 23.9 cells/μL." (PMID 24592945, 2014).